TKT (transketolase)
Description:
Catalyzes the transfer of a two-carbon ketol group from a ketose donor to an aldose acceptor, via a covalent intermediate with the cofactor thiamine pyrophosphate. Thus, catalyzes the reversible transfer of a two-carbon ketol group from sedoheptulose-7-phosphate to glyceraldehyde-3-phosphate, producing xylulose-5-phosphate and ribose-5-phosphate. The phosphate group of the substrate plays a role in stabilizing the substrate-thiamine intermediate while preventing the formation of the reactive enamine intermediate (Ref.28). Can also use fructose-6-phosphate as a ketose donor (Probable).
Synonyms: TK; HEL-S-48; HEL107; SDDHD; TKT1
Tractability: Small molecule: a structure with a bound ligand is known; a high-quality ligand is known; it has a high-quality binding pocket; it belongs to a druggable protein family. PROTAC: UniProt records ubiquitination sites on it; ubiquitination databases record sites on it; its protein half-life has been measured; a small molecule that binds it is known.
Target class: Enzyme; Transferase
Gene: Protein-coding gene on chromosome 3 (53,224,712 to 53,256,052, reverse strand). Ensembl gene ENSG00000163931.
Subcellular location (Human Protein Atlas): Nucleoplasm; Nuclear bodies; Nuclear speckles
Pathways (Reactome):
Metabolism: Insulin effects increased synthesis of Xylulose-5-Phosphate; Pentose phosphate pathway
Cellular responses to stimuli: NFE2L2 regulates pentose phosphate pathway genes
Gene Ontology:
Molecular function: calcium ion binding; magnesium ion binding; protein binding; protein homodimerization activity; transketolase activity; thiamine pyrophosphate binding; transketolase or transaldolase activity
Biological process: glyceraldehyde-3-phosphate biosynthetic process; pentose-phosphate shunt; pentose-phosphate shunt, non-oxidative branch; D-xylulose 5-phosphate biosynthetic process; glyceraldehyde-3-phosphate metabolic process
Cellular component: extracellular exosome; nuclear body; nuclear speck; nucleoplasm; vesicle; cytosol; peroxisome
Genetic constraint (gnomAD): Loss-of-function variants: 47 observed, 64.91 expected, observed/expected ratio (o/e) 0.72, 90% interval 0.57 to 0.92. The upper end of that interval is the gene's LOEUF score, 0.92, which puts it in group 3 of 6, group 1 being the genes least tolerant of losing a copy. Missense variants: 721 observed, 854.02 expected, observed/expected ratio (o/e) 0.84, 90% interval 0.79 to 0.9. Synonymous variants: 338 observed, 339.73 expected, observed/expected ratio (o/e) 0.99, 90% interval 0.91 to 1.09.
Homologues: Orthologues: chimpanzee TKT (99% identical), macaque TKT (99% identical), pig TKT (95% identical), mouse Tkt (95% identical), rat Tkt (94% identical), rabbit TKT (94% identical), dog TKT (92% identical), guinea pig TKT (89% identical), tropical clawed frog tkt (79% identical), zebrafish tkta (71% identical). Paralogues in human: TKTL2 (67% identical), TKTL1 (59% identical), BCKDHB (16% identical), PDHB (14% identical).
Diseases named in the same sentence as TKT in open-access papers:
TKT is named in the same sentence as 129 diseases in open-access papers, as found by Europe PMC text mining. Sharing a sentence is not in itself a finding about the gene and the disease. The quoted sentences say what the papers report.
Thiamine deficiency (40 papers, 2003 to 2026). Thiamine deficiency is a condition that occurs due to not enough thiamine (vitamin B1). "Thiamine concentrations and vitamer ratios of muscle, liver, and gonad tissues, as well as the activity and latency of transketolase, which is used as an indicator of thiamine deficiency, were investigated." (PMID 41531918, 2026). "Both thiamine deficiency and reduced TK levels can impair transketolase activity, possibly leading to a decrease within a week." (PMID 40243711, 2025). "Risk factors for Korsakoff’s syndrome include repetitive thiamine deficiency episodes and genetic predispositions, such as mutations in the transketolase enzyme that reduce its affinity for TPP." (PMID 40904570, 2025). "Additional biochemical assessments, such as erythrocyte transketolase activity and lactate/pyruvate levels, can indicate thiamine deficiency." (PMID 40507610, 2025). "The gold standard for detecting thiamine deficiency is activating transketolase activity (TKT) with TDP supplementation." (PMID 39113982, 2024). "Studies on mice models have reported that thiamine deficiency-induced decrease in transketolase activity leads to impaired neurogenesis in the hippocampus affecting cognitive abilities." (PMID 39271555, 2024). "Generally, thiamine deficiency is diagnosed by evaluating the response of erythrocytes transketolase activity to exogenous TPP, where higher responses reflect higher deficiencies and vice versa." (PMID 33608323, 2021). "The impact of clinically observed thiamine deficiency, ThDP concentration, their effect on transketolase enzyme, and consequences for interpretation of transketolase activity have been a topic of discussion for many years." (PMID 33354793, 2021). "There appears to be uncertainty in the literature regarding the prevalence of thiamine deficiency observed in malnourished patients, relating to two different methods of analysis, i.e. erythrocyte transketolase activity versus measurement of blood thiamine." (PMID 32884809, 2020). "A decreased TKT activity is presumed to be due to the decrease of vitamin B1 used for thiamine deficiency diagnosis." (PMID 31415630, 2019). "Another consequence of inclusion of older literature is heterogeneity in the means used to measure thiamine deficiency, with some studies having used the less accurate, indirect approach of erythrocyte transketolase activity assay to discern thiamine status." (PMID 30467601, 2019). "One study reported that the HPLC detection of TPP in whole blood or red blood cells is equally effective to the TKT activation ratio at determining thiamine deficiency." (PMID 31019473, 2019). "Consistent with this premise, thiamine deficiency decreases TKT activity and leads to PPP impairment and reduced neurogenesis in murine cortex and hippocampus during neurodevelopment." (PMID 31019473, 2019). "Measurement of erythrocyte TKT activity has been used for many years as a measure of thiamine deficiency." (PMID 30214418, 2018). "A concomitant concern is the need for more accessible and inexpensive tests to evaluate thiamine deficiency, as the current basal erythrocyte transketolase activity (ETK) assays remains unavailable in settings where they are most needed." (PMID 25781926, 2015). "Conversely, thiamine deficiency was found to decrease TKT mRNA levels and reduce TKT activity in neuroblastoma cells." (PMID 24280319, 2013). "Blood samples taken from 16 cases prior to treatment showed increased levels of erythrocyte transketolase activation coefficient, consistent with thiamine deficiency." (PMID 22205947, 2011). "Another possible explanation for the differences among people in their sensitivity to thiamine deficiency has focused on the assembly of functional transketolase." (PMID 15303623, 2003). "As a result, the Korsakoff ’s patients would be more susceptible to developing complications of thiamine deficiency than would people with a transketolase variant that more readily binds ThDP." (PMID 15303623, 2003).
Thiamine deficiency (continued). "Additionally, we measured the activity and latency of transketolase to understand the prevalence of thiamine deficiency in these stocks." (PMID 41531918, 2026). "In patients with suspected WE, determining blood thiamin concentrations or measuring the red blood cell transketolase activity could be a useful confirmatory test for thiamin deficiency, especially for cases with ambiguous presentations." (PMID 39949614, 2025). "There is limited information on relationships among biomarkers of thiamine status (whole blood thiamine diphosphate [ThDP], erythrocyte transketolase activity coefficient [ETKac], and human milk thiamine [MTh]) and clinical manifestations of thiamine deficiency." (PMID 38974350, 2024). "In myelinated structures of nervous tissues, levels of transketolase are high, which may explain the presence of peripheral neuropathy with thiamine deficiency, as seen in “dry” beriberi syndrome." (PMID 37189771, 2023). "This prevalence was higher than the prevalence of 13–30% reported by two studies in Lao PDR in which thiamine deficiency was defined both in terms of a basal erythrocyte transketolase (ETK) activity < 0.59 micromoles/min/gHb and an activation coefficient of ETK α > 31%." (PMID 35534778, 2022). "On November 9, 2009, blood samples taken from 16 cases prior to their treatment (drawn in September 2009) showed increased levels of erythrocyte transketolase activation coefficient in all samples, consistent with thiamine deficiency [Cobas mean = 1.34; range = 1.22 to 1.62 (normal = <1.25)]." (PMID 22205947, 2011). "Studies using rats found that transketolase activity may be reduced as much as 90 percent in the brain regions that are most sensitive to thiamine deficiency." (PMID 15303623, 2003). "Additionally, genetic variations affecting thiamine-utilizing enzymes, such as transketolase, may also predispose certain individuals to develop WE even with minimal thiamine deficiency." (PMID 40734843, 2025). "Overall, transketolase activity may be the most sensitive measure of thiamine deficiency." (PMID 15303623, 2003). "Nonetheless, if administering B1 alone leads to increased TKT activity, reduced PAR and/or FAR effect, and prompt clinical recovery, it is reasonable to infer that thiamine deficiency played a role in the illness." (PMID 39113982, 2024). "The percentage increase in transketolase activity following addition of TDP represents the patient’s thiamine status (> 15% and > 25% indicating moderate and severe thiamine deficiency respectively)." (PMID 35484175, 2022). "Without a doubt, the most reliable method to establish thiamine deficiency is measuring erythrocyte transketolase activity (at baseline and after addition of thiamine pyrophosphate)." (PMID 38920544, 2024). "TKTL1 shows a greater preference for xylulose-5-phosphate as a substrate compared to TKT, which might have lower TDP affinity, making it more susceptible to thiamine deficiency." (PMID 39113982, 2024). "The strong negative correlation between specific endogenous transketolase activity and the proportion of transketolase apoenzymes clearly suggests thiamine deficiency in the liver tissue." (PMID 31895939, 2020). "The even stronger negative correlations between specific endogenous transketolase activity and the proportion of transketolase apoenzymes in brain tissue further demonstrates thiamine deficiency in the studied eastern Baltic cod." (PMID 31895939, 2020). "Overall, researchers to date have found no consistent correlation between genetically determined transketolase variants and a person’s sensitivity to thiamine deficiency." (PMID 15303623, 2003). "It is important to note that these adverse effects of alcohol-induced thiamine deficiency, particularly the reduction of transketolase activity, can occur even in alcoholics who do not show evidence of WE or WKS." (PMID 15303623, 2003).
Thiamine deficiency (continued). "Moreover, blood thiamine content does not correlate with TKT activity at initial steps (or subtle) thiamine deficiency." (PMID 39113982, 2024). "However, a study showed that thiamine deficiency reduces mRNA levels of the enzyme transketolase and the component E1-subunit beta of the PDH, but no alteration was observed in PDHa1 and OGDH genes in three human cell types." (PMID 39364430, 2024). "Erythrocyte transketolase activity was assessed to determine whether thiamine deficiency was contributing to the clinical myopathy, independent of potassium status." (PMID 36669053, 2023). "Either way, chronic thiamine deficiency may cause loss of apo‐transketolase and evidence suggests that this is caused by an effect on synthesis rather than catabolism of transketolase." (PMID 33354793, 2021). "In the absence of testing for ThDP levels or transketolase activity, a clinician might presume the diagnosis of thiamine deficiency based on the clinical setting." (PMID 33305487, 2021). "Also, although testing on 16 cases showed increased levels of erythrocyte transketolase activation coefficient in all samples, consistent with thiamine deficiency, we did not test all cases, nor did we test controls." (PMID 22205947, 2011). "Transketolase from the Korsakoff ’s patients could function normally when sufficient thiamine or ThDP was present; under conditions of thiamine deficiency, however, the transketolase molecules would not be able to bind enough ThDP to maintain normal enzyme activity." (PMID 15303623, 2003).
breast cancer (28 papers, 2014 to 2025). A primary or metastatic malignant neoplasm involving the breast. "TKT is highly expressed in breast cancer tissues and metastatic lymph nodes, which is associated with a poor prognosis." (PMID 38434975, 2024). "The expression of TKT is associated with tumor size and high TKT expression is associated with poor prognosis in a mouse model of breast cancer." (PMID 34552932, 2021). "They found that TKT expression is higher in lymph node metastases, and is associated with poor survival compared with primary tumor or normal tissues of breast cancer patients." (PMID 31947673, 2020). "Combining docetaxel and/or doxorubicin with a TKT inhibitor enhances the sensitivity of breast cancer cells to these two chemotherapeutic agents, thereby exerting a more potent inhibitory effect on cell proliferation." (PMID 40227333, 2025). "According to the literature review, USP3 promotes GC cell migration and invasion; SLC7A6 hasn’t been reported in studies related to cancer; IGF2BP1 accelerates GC progression; and TKT facilitates breast cancer metastasis." (PMID 35739527, 2022). "In breast cancer cell lines, silencing of TKT led to cell cycle arrest coupled with metabolic flux towards glycolysis away from nucleotide biosynthesis." (PMID 34117285, 2021). "Oxythiamine, an inhibitor of TKT, also increases the response of breast cancer cells to doxorubicin or docetaxel." (PMID 34552932, 2021). "It has been suggested that the expression of G6PD and transketolase (TKT) are positively correlated to the decreased overall and relapse-free survival in breast cancer." (PMID 33489906, 2020). "As redox homeostasis plays an important role in breast cancer progression, we assessed the effect of TKT and G6PD silencing on ROS levels." (PMID 29290982, 2017). "Herein, we silenced the most important enzymes of this pathway — glucose-6-phosphate dehydrogenase (G6PD) and transketolase (TKT) — in the human breast cancer cell line MCF7." (PMID 29290982, 2017). "In conclusion, this is the first study investigating the expression of TKT and TKT-like enzymes in canine mammary tumors and hyperplastic lesions." (PMID 28143530, 2017). "We finally provided strong evidence to support the fact that high expression of TKT and G6PD is associated with poor outcome in breast cancer patients." (PMID 29290982, 2017). "First, G6PD and TKT were silenced in the breast cancer cell line MCF7 and the impact on cell proliferation, survival and cell cycle was assessed." (PMID 29290982, 2017). "In addition, enhanced expression profile of the pentose phosphate pathway-related enzymes such is 6PGDH and TKT is also evident in breast cancer, especially in HER-2 and triple negative types, which is again associated with poor clinical prognosis." (PMID 35917304, 2022). "For example, in breast cancer, TKT promotes metastasis through regulatingα-Ketoglutarate signaling pathway, and it has been shown that TKT enters the nucleus and activates the EGFR pathway, thereby promoting proliferation, viability, and migration of liver cancer." (PMID 35110545, 2022). "Considering the critical role of the STAT3 signaling pathway in HDGF/TKT-driven breast cancer radioresistance, we assessed the effects of Stattic treatment combined with HDGF-depletion on breast cancer radioresistance using the MDA-MB-231 cells xenograft models." (PMID 34376200, 2021). "The potential association of HDGF with TKT and STAT3 promotes STAT3-Y705 phosphorylation and inhibits STAT3-S727 phosphorylation enhancing STAT3 transcriptional activity, thereby increasing tumor radioresistance in breast cancer." (PMID 34376200, 2021). "High expression of PPP-related enzymes, such as 6PGD and TKT, is reported in breast cancer." (PMID 34552932, 2021). "Importantly, we showed using breast cancer patient datasets that expression of both enzymes is positively correlated and that high expression levels of G6PD and TKT are associated with decreased overall and relapse-free survival." (PMID 29290982, 2017).
breast cancer (continued). "Finally, we have also shown that high expression levels of G6PD and TKT correlate with poor overall and relapse-free survival in several breast cancer patient datasets." (PMID 29290982, 2017). "In breast cancer Transketolase was identified as a potential target against tumor growth." (PMID 26861291, 2016). "In order to detect the effect of Nrf2 on PPP in breast cancer, expression of G6PD and TKT was detected by RT‐PCR and western blotting in MCF‐7 and MDA‐MB‐231 cells." (PMID 30809937, 2019). "We observed increased expression of TKT and TKTL1 in the proposed multistep carcinogenesis of CMT, thus indicating that PPP is a cancer metabolism-related pathway also in canine mammary tumors." (PMID 28143530, 2017). "To understand the biological and metabolic role of these two enzymes in breast cancer, we separately silenced TKT (siTKT) and G6PD (siG6PD) in the breast cancer cell line MCF7 by using specific small interference RNAs (siRNA)." (PMID 29290982, 2017). "The metabolomic changes in the global biochemical profiles of RS4 leukemia cells and MCF-7 breast cancer cells treated with thiaminase are consistent with inhibition of BCKDH complex, pyruvate dehydrogenase complex, and transketolase inhibition." (PMID 24454921, 2014). "TKT and TKTL1 protein expression was investigated by immunohistochemistry in canine normal (N = 6) and hyperplastic glands (N = 3), as well as in benign (N = 11) and malignant mammary tumors (N = 17)." (PMID 28143530, 2017). "Expression levels of transketolase (TKT)—an antagonist of α-KG—could, for instance, regulate the metabolic switch through HIF-1α and PDH2 via the α-KG-dependent dioxygenase signaling and the transcription of SDH and FH to control breast cancer metastasis." (PMID 32300553, 2020). "Reactive bands were observed for TKTL1 at a slightly lower molecular weight (approx. 58 kDa) than TKT, with different signal intensities in normal and in mammary tumor tissues, as well as in the positive control; again, no signal was detected in the negative control." (PMID 28143530, 2017). "To date, no studies have characterized the protein expression of TKT and TKTL1 and their potential role in the onset of canine mammary tumors." (PMID 28143530, 2017). "Moreover, the glycolysis pathway and the non-oxidative PPP are further interlinked; for example, TKT depletion resulted in decreased levels of glycolytic enzymes including HK, PFK, and PKM2 in breast cancer cells." (PMID 34677415, 2021).